GLIS1 (GLIS family zinc finger 1)
Description:
Acts both as a repressor and an activator of transcription. Binds to the consensus sequence 5'-GACCACCCAC-3' (By similarity). By controlling the expression of genes involved in cell differentiation inhibits the lineage commitment of multipotent cells. Prevents, for instance, the differentiation of multipotent mesenchymal cells into adipocyte and osteoblast (By similarity).
Synonyms: FLJ36155
Tractability: No criterion of Open Targets' tractability assessment is met for any kind of drug.
Gene: Protein-coding gene on chromosome 1 (53,506,232 to 53,739,164, reverse strand). Ensembl gene ENSG00000174332.
Subcellular location: Nucleus
Subcellular location (Human Protein Atlas): Nucleoplasm; Cytosol; Nuclear bodies
Gene Ontology:
Molecular function: protein binding; sequence-specific double-stranded DNA binding; DNA-binding transcription activator activity, RNA polymerase II-specific; DNA-binding transcription factor activity, RNA polymerase II-specific; RNA polymerase II cis-regulatory region sequence-specific DNA binding; RNA polymerase II transcription regulatory region sequence-specific DNA binding
Biological process: negative regulation of transcription by RNA polymerase II; positive regulation of transcription by RNA polymerase II; regulation of transcription by RNA polymerase II
Cellular component: nuclear body; nucleoplasm; nucleus
Genetic constraint (gnomAD): Loss-of-function variants: 23 observed, 54.3 expected, observed/expected ratio (o/e) 0.42, 90% interval 0.3 to 0.6. The upper end of that interval is the gene's LOEUF score, 0.6, which puts it in group 2 of 6, group 1 being the genes least tolerant of losing a copy. Missense variants: 1,034 observed, 987 expected, observed/expected ratio (o/e) 1.05, 90% interval 1 to 1.1. Synonymous variants: 450 observed, 436.01 expected, observed/expected ratio (o/e) 1.03, 90% interval 0.95 to 1.12.
Homologues: Orthologues: chimpanzee GLIS1 (99% identical), pig GLIS1 (90% identical), rabbit GLIS1 (86% identical), rat Glis1 (84% identical), mouse Glis1 (83% identical), guinea pig GLIS1 (82% identical), macaque GLIS1 (75% identical), dog GLIS1 (71% identical), zebrafish glis1b (37% identical), tropical clawed frog glis1 (31% identical). Paralogues in human: GLIS3 (37% identical), GLI2 (28% identical), GLI3 (27% identical), GLI1 (19% identical), GLIS2 (17% identical), ZIC5 (15% identical), ZIC2 (14% identical), ZIC1 (14% identical), ZXDC (14% identical), ZXDB (14% identical), ZXDA (14% identical), ZIC3 (13% identical), and 2 more.
Diseases named in the same sentence as GLIS1 in open-access papers:
GLIS1 is named in the same sentence as 32 diseases in open-access papers, as found by Europe PMC text mining. Sharing a sentence is not in itself a finding about the gene and the disease. The quoted sentences say what the papers report.
breast carcinoma (5 papers, 2014 to 2022). "GLIS1-3 have been implicated in various malignancies, including leukemia, thyroid cancer, and breast cancer." (PMID 35681527, 2022). "Similarly, hypoxia-induced GLIS1 expression in MDA-MB-231 breast carcinoma cells caused an increase in WNT5A expression and cell migration." (PMID 35681527, 2022). "In MMTV-Cut like homeobox 1 (CUX1) transgenic mice, a mouse model used to study breast cancer development, GLIS1 was found to be highly expressed in a subset of breast tumors with elevated WNT expression." (PMID 35681527, 2022). "A previous study revealed that GLIS1 is highly expressed in several cancer cells, notably breast cancer cells, with WNT gene expression which correlated the epithelial-to-mesenchymal transition (EMT) signature." (PMID 35216340, 2022). "A recent report suggested that low miR-1-3p expression from CAFs-derived EVs contributed to the promotion of breast cancer progression and metastasis through upregulation of GLIS1 in this subset of cancer." (PMID 35216340, 2022). "We conclude that p110 CUX1 and GLIS1 can cooperate in the activation of Wnt genes in human breast cancer cells." (PMID 25217618, 2014). "We conclude that higher expression of GLIS1 in mammary tumor cells from MMTV-CUX1 transgenic mice leads to the transcriptional activation of several Wnt genes." (PMID 25217618, 2014). "We did not, however, observe the upregulation of stem or progenitor cell markers in mammary tumors that otherwise displayed Glis1, CUX1 and Wnt expression." (PMID 25217618, 2014). "By comparing expression profiles of laser-capture microdissected mammary tumors, we identify Glis1 as a transcription factor that is highly expressed in the subset of tumors with elevated Wnt gene expression." (PMID 25217618, 2014). "Taken together, GLIS1 overexpression in cancer cells might be involved in cancer cell migration, invasion, and metastasis in in human leukemic or breast cancers." (PMID 35216340, 2022). "In addition, GLIS1, a novel hypoxia-inducible transcription factor, was reported to increase the migration and invasion capacities of breast cancer cells by upregulating Wnt5a, and Wnt5a levels were associated with poorer prognosis in breast cancer patients." (PMID 33754039, 2021). "We verified whether high WNT gene expression correlates with that of CUX1 and GLIS1 in human breast cancers." (PMID 25217618, 2014). "Furthermore, by comparing the expression profiles of laser-capture microdissected tumor cells from a panel of randomly selected MMTV-CUX1 mammary tumors, we identified GLIS1 as a transcription factor that is significantly overexpressed in tumors with high WNT gene expression." (PMID 25217618, 2014). "Overall, A correlation between CUX1 and WNT levels was observed in the 3 out of 3 breast cancer datasets that had a relevant CUX1 probe (Esserman, Gluck, TCGA), and between Glis1 and WNT in 7 out of 8 datasets with Glis1 probes." (PMID 25217618, 2014). "Meta-analysis of human breast cancer datasets showed that elevated WNT gene expression also correlated with high levels of CUX1 and GLIS1." (PMID 25217618, 2014). "In this study, we presented evidence from transgenic mouse models, tissue culture systems and human breast cancer databases implicating the CUX1 and GLIS1 transcription factors in the autocrine activation of the Wnt/β-catenin pathway." (PMID 25217618, 2014). "Expression profiling analysis in human and mouse mammary tumors suggested that high Wnt gene expression requires both CUX1 and GLIS1." (PMID 25217618, 2014). "Besides MYC itself, we find upregulation of other breast cancer stem cell factors (SOX2, SOX18, THY1, EYA1, GLI2, SALL1, GLIS1, CXCR4), suggesting that MYC HME cells adopt a stem-like state." (PMID 31942031, 2020).
cardiomyopathy (2 papers, 2017 to 2019). A disease of the heart muscle or myocardium proper. "However, Yoshioka and Dowdy also successfully generated iPSCs from adult human fibroblasts of 54- to 77-year-old healthy donors and from a 24-year-old cardiomyopathy patient using srRNA encoding the reprogramming factors Oct4, Sox2, Klf4, Glis1, and cMyc." (PMID 31320906, 2019). "We found that five factor srRNA (5F-srRNA), including OCT4, KLF4, SOX2, GLIS1 and c-MYC (OKSi-GM), significantly increased iPSC generation in six different adult human fibroblasts, including old adult fibroblasts and a cardiomyopathy patient donor." (PMID 28750082, 2017). "We found that a single transfection of a five factor (5F) srRNA, containing OCT4, KLF4, SOX2, GLIS1 and c-MYC, robustly generated iPSCs from adult human fibroblasts aged 54 to 77 and from a 24 year old cardiomyopathy patient donor." (PMID 28750082, 2017).
hepatocellular carcinoma (2 papers, 2023 to 2024). A malignant tumor that arises from hepatocytes. "GLI-similar 1 (GLIS1), a zinc finger protein, causes CD8+ T cell exhaustion via the SGK1-STAT3-PD1 pathway in hepatocellular carcinoma (HCC)." (PMID 38915413, 2024).
renal fibrosis (2 papers, 2025). A final common manifestation of a wide variety of chronic kidney diseases characterized by glomerulosclerosis and tubulointerstitial fibrosis. "Further studies are necessary to determine whether the protective mechanism of Glis1 in renal fibrosis is associated with lactylation." (PMID 40207870, 2025). "Glis1 is a protective gene that significantly influences cellular ageing and renal fibrosis by maintaining mitochondrial stability and cellular integrity, thereby delaying age‐related renal fibrosis progression." (PMID 40207870, 2025). "Notably, GLIS1 alleviates renal fibrosis during kidney aging." (PMID 40977851, 2025).
Alzheimer disease (1 paper, 2023). A progressive, neurodegenerative disease characterized by loss of function and death of nerve cells in several areas of the brain leading to loss of cognitive function such as memory and language. "Some of these genes have already been linked to serious neurological conditions, such as SCN7A, which has been associated with amyotrophic lateral sclerosis, GLIS1 with Parkinson’s Disease and SPARCL1 with neuroinflammation in Alzheimer’s Disease." (PMID 36980268, 2023).
colon cancer (1 paper, 2020). "With the generation of the associated data, we will verify the role of GLIS1_cg22444507_ITIH5 in colon cancer." (PMID 32849837, 2020).
congenital hypothyroidism (1 paper, 2021). A thyroid hormone deficiency present from birth. "We hypothesize that reduced expression of a set of genes rather than one particular single gene is causing the TM abnormalities and high IOP in GLIS1 deficiency, as we reported for the development of congenital hypothyroidism and neonatal diabetes in Glis3-KO mice." (PMID 34385434, 2021).
cystic renal disease (1 paper, 2025). "Additionally, GLIS1 is involved in the regulation of cystic renal disease progression." (PMID 40977851, 2025).
diabetic nephropathy (1 paper, 2025). "In diabetic nephropathy, researchers found that GLIS family zinc finger 1 (Glis1) can bind and interact with lactoyltransferase KAT5, reducing the interaction of histone and KAT5, decreasing the lactylation level of histone, and alleviating the senescence of renal tubular epithelial cells." (PMID 40153584, 2025).
glaucoma (1 paper, 2021). Increased pressure in the eyeball due to obstruction of the outflow of aqueous humor. "Transcriptome and cistrome analyses identified several glaucoma- and extracellular matrix-associated genes as direct transcriptional targets of GLIS1." (PMID 34385434, 2021). "We also identified a significant association between GLIS1 variant rs941125 and glaucoma in humans (P = 4.73 × 10−6), further supporting a role for GLIS1 into glaucoma etiology." (PMID 34385434, 2021). "Here, the authors identify the transcription factor, GLIS1, as a critical regulator of TM maintenance and intraocular pressure, and as a glaucoma risk gene." (PMID 34385434, 2021). "Thus, Glis1-KO mice provide us with a valuable model to uncover cellular and molecular mechanisms that underlie the regulation of TM maintenance and ocular drainage tissue homeostasis and potentially lead to new insights into the pathogenesis of glaucoma." (PMID 34385434, 2021). "Our genetic studies provide further validation for the role of GLIS1 in glaucoma pathogenesis and extend our findings in mice to humans." (PMID 34385434, 2021). "Our data suggest that the increased IOP observed in the Glis1-KO mice correlates with reduced AqH outflow and might involve dysfunction of the TM, a major cause of elevated IOP and glaucoma." (PMID 34385434, 2021). "Analysis of the combined RNA-Seq and ChIP-Seq data showed that the transcription of several of the differentially expressed genes with roles in TM, IOP, and glaucoma, were directly regulated by GLIS1 and included MYOC, LTBP2, CHI3L1, HMGA1, CYP1B1, and LOXL1-4." (PMID 34385434, 2021). "Importantly, we have detected significant associations between common genetic variants in the GLIS1 region and POAG in humans, thereby supporting the role of GLIS1 as a glaucoma risk gene." (PMID 34385434, 2021). "Together, these findings support a role for GLIS1 in glaucoma pathogenesis in humans." (PMID 34385434, 2021). "In addition, we identified several transcriptional targets of GLIS1 in TM cells that previously have been implicated in TM-related functions, IOP homeostasis, and ocular hypertension/glaucoma, including MYOC, ADAMTS10, LTBP2, LOXL1, TGFBR3, CYP1B1, and EFEMP15,28,43,44." (PMID 34385434, 2021). "These variants may impact TM functions and compromise AqH drainage by altering GLIS1 expression and/or function and leading to elevated IOP and glaucoma." (PMID 34385434, 2021). "In addition to these ECM and adhesion-related genes, transcriptome analysis showed that GLIS1 impacts the expression of several other TM-, IOP-, and glaucoma-related genes, including MYOC and CYP1B1." (PMID 34385434, 2021).
glioblastoma (1 paper, 2023). The most malignant astrocytic tumor (WHO grade IV). "The forest plot displayed that GLIS1 could significantly affect the OS of GBMLGG (lower grade glioma and glioblastoma, p = 0.001), LGG (p = 0.003), SKCM (p = 0.003), SARC (sarcoma, p = 0.021), THCA (p = 0.043), and PRAD (p = 0.017) patients." (PMID 38203661, 2023).
Graves disease (1 paper, 2021). Graves' disease is an autoimmune disorder that leads to overactivity of the thyroid gland (hyperthyroidism).It is caused by an abnormal immune system response that causes the thyroid gland to produce too much thyroid hormones. "However, our analysis of serum T3, T4, and TSH showed that their levels were not significantly different between WT and Glis1-KO C57BL/6NCrl mice indicating that this phenotype was not related to the development of Graves’ disease." (PMID 34385434, 2021).
leukemia (1 paper, 2022). A malignant (clonal) hematologic disorder, involving hematopoietic stem cells and characterized by the presence of primitive or atypical myeloid or lymphoid cells in the bone marrow and the blood. "GLIS1-3 have also been implicated in several malignancies, including breast and colorectal cancer, and leukemia." (PMID 35681527, 2022).
medulloblastoma (1 paper, 2021). A malignant, invasive embryonal neoplasm arising from the cerebellum. "Of note, GLIS1 is expressed in Daoy but not in UW-228 cells, highlighting differences in the gene expression patterns of these two medulloblastoma cell lines." (PMID 34680287, 2021). "The seven circRNAs, FKBP8, SMARCA5, GLIS1, BACH1, ZKSCAN1, CDYL, and OGDH, with a reduced expression in medulloblastoma versus cerebellum, while their corresponding linear mRNAs do not follow this change of expression pattern, were selected for further analysis." (PMID 34680287, 2021).
ovarian carcinoma (1 paper, 2022). A malignant neoplasm originating from the surface ovarian epithelium. "In summary, we, for the first time, revealed that elevated GLIS1 expression in patient-derived CAFs of OSCs with metastatic potential, and that silencing GLIS1 in mCAFs reduced motility, adhesion, angiogenesis, and metastasis of ovarian cancer cells in vitro and in vivo." (PMID 35216340, 2022). "In the present study, we demonstrated that GLIS1 in CAF, not in cancer cell itself, induced the cancer cell migration, invasion, and metastasis in ovarian cancers." (PMID 35216340, 2022).
sarcoidosis (1 paper, 2023). Sarcoidosis is a multisystemic disorder of unknown cause characterized by the formation of immune granulomas in involved organs. "Unlike myofibroblasts and ECM fibroblasts which enriched fibroblast activation TFs, such as GLIS1 and TRPS1, only in sarcoidosis, endothelial fibroblasts showed enrichment of FLI1, a fibroblast activation suppressor TF, and GATA2, an endothelial cell TF, strictly in sarcoidosis." (PMID 37576111, 2023).
triple-negative breast carcinoma (1 paper, 2022). An invasive breast carcinoma which is negative for expression of estrogen receptor (ER), progesterone receptor (PR), and human epidermal growth factor receptor 2 (HER2). "GLIS1 was also reported to be related to a worse prognosis in ALL and triple negative breast cancer." (PMID 35216340, 2022).
cancer (8 papers, 2014 to 2025). A tumor composed of atypical neoplastic, often pleomorphic cells that invade other tissues. "Our work has found that the expression of GLIS1 varies between normal tissue and tumor tissues in various cancer types and is significantly downregulated in PCa, and decreased GLIS1 expression is associated with unfavorable prognosis in PCa." (PMID 38203661, 2023). "These tumors all showed that GLIS1 was associated with patient outcome, suggesting that GLIS1 has great potential to serve as a prognostic indicator molecule in pan-cancer." (PMID 38203661, 2023). "In addition, the second and third significant prognostic genes, DACH1 and GLIS1, have been widely reported that they are associated with the regulation of tumors and cancers." (PMID 35453785, 2022). "GLI-similar 1 (GLIS1) downregulation in CD8+ T cells slows cancer progression, increases infiltration, and enhances the anti-PD1 response in HCC." (PMID 40122853, 2025). "Results showed that GLIS1 was differentially expressed between normal and tumor tissues in various cancer types and was significantly low-expressed in PCa." (PMID 38203661, 2023). "We systematically explored the expression and prognostic values of GLIS1 in cancers using multiple databases." (PMID 38203661, 2023). "We found that GLIS1 was the most significantly overexpressed in mCAFs, and GLIS1 derived from mCAFs is essential for cancer cell invasion and migration by using in vitro assay and in vivo xenograft experiments." (PMID 35216340, 2022). "Another study showed that the hypoxia-inducing factors HIF2α, together with JUN, regulated GLIS1 transcription in various cancer cells." (PMID 35216340, 2022). "In cancers and during cellular reprogramming, GLIS1 activates the WNT signaling pathway, especially several WNTs." (PMID 35087831, 2021). "High expression of GLIS1 in cancers is particularly striking considering that Glis1 expression in mouse was found to be elevated in unfertilized eggs and one-cell embryos but weak in adult tissues." (PMID 25217618, 2014). "Regarding tumors, GLIS1 in cancer cells is involved in cell migration, invasion, and tumorigenesis." (PMID 38203661, 2023). "We also examined cancer cell proliferation using the CCK-8 assay to determine whether GLIS1 in CAF is involved in cancer cell proliferation." (PMID 35216340, 2022). "In regard to tumors, GLIS1 in various cancer cells might be involved in migration, invasion, and epithelial–mesenchymal transition (EMT), as well as oncogenesis." (PMID 35216340, 2022). "Analysis of human cancer datasets confirms that elevated WNT gene expression is associated with high levels of CUX1 and GLIS1 and correlates with genes of the epithelial-to-mesenchymal transition (EMT) signature: VIM, SNAI1 and TWIST1 are elevated whereas CDH1 and OCLN are decreased." (PMID 25217618, 2014). "However, the physiological roles of GLIS1 in cancer are just beginning to be recognized." (PMID 35216340, 2022). "TFs associated with PIK3CA mutations were involved in WNT signaling, epithelial–mesenchymal transition, and cancer stem cell transition, including ELF3, TFEC, STAT4, STAT5B, NFATC1, GLIS1, CDC5L and AR." (PMID 36243974, 2022). "Both GLIS1 and NANOG have been indicated to activate certain components of the WNT pathway in reprogramming, and WNT and LIN28 co-amplify the expression of their target genes in cancer cells." (PMID 31806618, 2019). "Indeed, the present study strongly suggests that GLIS1 and CUX1 play an important role in the promotion of both the Wnt signaling and the EMT phenotype in many cancer cells." (PMID 25217618, 2014). "However, there have been no previous reports about GLIS1 expression in CAF and its role on cancer cells." (PMID 35216340, 2022). "In addition, primary cancer cells did not express DCHS1 and GLIS1 mRNA and protein." (PMID 35216340, 2022).